NLRP3 (NLR family pyrin domain containing 3)
Diseases named in the same sentence as NLRP3 in open-access papers (continued):
Sharing a sentence is not in itself a finding about the gene and the disease.
Sepsis (continued). "Moreover, in our in vivo study, the silence of TXNIP markedly decreased the expression level of NLRP3/caspase-1 pathway-related genes and alleviated the damage of the kidney under the sepsis conditions, which is similar with the result of miR-30c-5p treatment." (PMID 32892306, 2021). "Consequently, we measured the production of IL-6, TNF-α and IL-1β in sepsis patients and healthy controls and in PBMCs under in vitro LPS stimulation to investigate the effect of the NLRP3 29940 G>C variation on the production of these related cytokines." (PMID 34172780, 2021). "However, the mechanism and effect of the NLRP3 inflammasome on the pathophysiology of sepsis need further study." (PMID 33860064, 2021). "In conclusion, our data suggested that miR-30c-5p negatively controlled the NLRP3 signal pathway-related pyroptosis and sepsis-induced injury via TXNIP, indicating that this axis might be a positive therapeutic target for the patient with SAKI." (PMID 32892306, 2021). "And colleagues found that melatonin could inactivate NF-κB induction, reduce NLRP3 expression and alleviate the inflammatory state of sepsis." (PMID 34305952, 2021). "Therefore, it is important to understand how NLRP3 participates in the inflammatory response of macrophages in sepsis." (PMID 34220338, 2021). "Additionally, it is uncertain if deletion of the NLRP3 inflammasome improves both systolic and diastolic dysfunction in sepsis." (PMID 34472725, 2021). "Next, we explored whether PPARγ was functionally involved in GPR43’s induction of NLRP3 Inflammasome in sepsis model." (PMID 34584017, 2021). "Many studies have highlighted the role of Nlrp3 inflammasome/IL-1β pathway in promoting CVD and the link between inflammation and CVD is further highlighted by the link between sepsis survivor and higher risk of having a heart attack or stroke." (PMID 34395445, 2021). "Because NLRP3/IL‐1β pathway inhibition attenuates cardiac atrophy and cardiomyopathy in sepsis, it could be useful to prevent septic cardiomyopathy." (PMID 34472725, 2021). "Activation of the NLRP3 inflammasome promoted endothelial dysfunction of early sepsis in mice." (PMID 34011327, 2021). "However, our results excluded a point that the inhibition of GPR43 promoted inflammatory reactions in sepsis model by the activation of NLRP3 inflammasome, and its activation mechanism was unclear." (PMID 34584017, 2021). "This study validated the mechanism of how GPR43 regulated NLRP3 Inflammasome in sepsis model." (PMID 34584017, 2021). "Second, diastolic cardiac function was preserved in Nlrp3 KO mice during sepsis." (PMID 34472725, 2021). "Inhibition of NLRP3 has a protective role in lethal sepsis through neuroimmune modulation." (PMID 34257519, 2021). "Muscle wasting is linked to the inflammatory response occurring during the acute phase of sepsis, and might potentially be mediated by the NLRP3 inflammasome." (PMID 34831246, 2021). "The NLRP3 inflammasome, an intracellular signaling complex that activates potent inflammatory cascade responses, is relevant in numerous infectious and autoimmune diseases like peritonitis, sepsis, T2D, systemic lupus erythematosus, and rheumatoid arthritis." (PMID 34566976, 2021). "The NLRP3 inflammasome is involved in many inflammatory diseases, including sepsis." (PMID 34220338, 2021). "In contrast, genetic depletion of core components of inflammasomes, such as Nlrp3, Casp1, Casp11, and gasdermin D (Gsdmd), protects against septic shock or lethal endotoxemia in mice, turning them into a promising target for treatment of sepsis." (PMID 33796108, 2021). "GPR43 agonist presented abdominal macrophage to induce NLRP3 in the model of sepsis." (PMID 34584017, 2021). "Next, we explored whether NLRP3 Inflammasome is an important target of GPR43 in sepsis-induced inflammatory reactions model." (PMID 34584017, 2021). "Recently, some studies have unveiled that STING could activate NLRP3 inflammasome and trigger pyroptosis during sepsis." (PMID 33252860, 2020).
Sepsis (continued). "Notably, inhibition of melatonin against Nod-like receptor protein 3 (NLRP3) inflammasome activation in the heart during sepsis implied cardioprotective effects of melatonin against sepsis-induced acute myocardial injury." (PMID 32373063, 2020). "We further hypothesized that inhibition of NLRP3 would improve renal function and prevent immune cell infiltration into the lungs to attenuate multi-organ injury induced by polymicrobial sepsis." (PMID 32555710, 2020). "Studies have also shown that the NLRP3 inflammasome contributes to sepsis." (PMID 32131850, 2020). "In addition, NLRP3 inflammasome signaling has been proven to exacerbate cell apoptosis in sepsis-induced acute respiratory distress syndrome." (PMID 33324236, 2020). "Thus, our findings agree with these previous studies and indicate that MV promotes the sepsis-activated NLRP3 inflammasome, which is negatively regulated by autophagy." (PMID 32117318, 2020). "Considering the complicated interaction of ROS and NLRP3 inflammasomes, targeting the signal of ROS/NLRP3 inflammasomes may be a potential strategy for sepsis therapy." (PMID 33324236, 2020). "Cortistatin deactivates NLRP3 inflammasome activity to reduce myocardial injury induced by sepsis." (PMID 33324236, 2020). "NLRP3 is an inflammasome complex whose dysregulated activation is associated with AKI and sepsis." (PMID 32626733, 2020). "We have recently shown that NLRP3 inflammasome activation occurs in platelets and is associated with renal glomerular injury and pulmonary edema in the cecal-ligation and puncture (CLP) rat model of sepsis." (PMID 32555710, 2020). "Therefore, autophagy has a protective role in sepsis through dampening inflammatory response by removing NLRP3 activator, such as damaged mitochondrial and ROS, as well as degrading NLRP3 inflammasome components." (PMID 33163006, 2020). "Some studies have shown that NLRP3 is a key factor involved in inflammation in sepsis." (PMID 33182702, 2020). "Sestrin 2 induces mitophagy to clean damaged mitochondria and inhibit NLRP3 activation in sepsis." (PMID 33324236, 2020). "Therefore, T. gondii GRA9 is a potential candidate for a therapeutic agent acting via interaction with NLRP3 for sepsis." (PMID 33182702, 2020). "However, the production of IL-18 is increased by lipopolysaccharide-stimulated NLRP3 inflammasome activation, indicating that IL-18 levels are increased in patients with sepsis." (PMID 32381117, 2020). "Moreover, CD39 overexpression inhibited the NLRP3 inflammasome activation, which decreased inflammation and mitigated sepsis-induced organ injury." (PMID 33519492, 2020). "Future studies should therefore address the roles of ROS and NLRP3 inflammasomes in various pathophysiological and immunology stages in sepsis, to identify ways to manipulate mitochondrial damage and/or mitophagy as a means of modulating apoptosis and inflammatory responses." (PMID 33324236, 2020). "The regulation of NLRP3 inflammasome activation is important for both stages of sepsis." (PMID 33182702, 2020). "NLRP3 inhibitors therefore have advantages in the possible treatment of sepsis." (PMID 33324236, 2020). "In order to clarify the role of NO in regulating the NLRP3 inflammasome associated with AKI, a specific inducible NO synthase (iNOS) inhibitor was administered in addition to Arg in a mouse model of polymicrobial sepsis in this study." (PMID 32454788, 2020). "Our recent study proposed that STING may drive NLRP3 inflammasome‐mediated pyroptosis and cellular injury in sepsis‐induced cardiac injury." (PMID 33252860, 2020). "Evidence for sepsis treatment strategies by targeting NLRP3, ROS, autophagy, and mitochondria." (PMID 33324236, 2020). "Impairment of NLRP3 was associated with increased mortality in sepsis patients suggesting that P2X7 activation plays a detrimental role in sepsis." (PMID 32477120, 2020).
Sepsis (continued). "In summary, our results suggest that ethyl pyruvate treatment might improve cognitive function in sepsis through inhibition of the NLRP3 inflammasome." (PMID 32517686, 2020). "Thus, additional studies are needed to clarify short and long-term effects of NLRP3 treatment on different organ systems and outcomes in response to sepsis." (PMID 32555710, 2020). "Therefore, accumulating studies have clarified the mechanism through which the NLRP3 inflammasome is regulated; however, the role of NLRP3 inflammasome in sepsis awaits further investigations." (PMID 33679687, 2020). "The activation of NLRP3 inflammasome has been proved to contribute to the inflammatory response of sepsis-induced AKI, which causes an impaired kidney morphology, increased renal tubular cell apoptosis, and NLRP3-dependent proinflammatory cytokine (i.e., IL-1β and IL-18) production." (PMID 32454788, 2020). "This suggests that NLRP3 inflammasome impairment during sepsis is transitory." (PMID 31221993, 2019). "This study suggests that NLRP3 may be a mechanism by which platelets regulate the exaggerated inflammation that occurs in sepsis." (PMID 31054188, 2019). "•NLRP3 inflammasome is involved in the development in sepsis-induced cardiomyopathy." (PMID 31121492, 2019). "This increase in expression was reduced by MRS/MRM treatment, indicating that methane could inhibit the NLRP3/caspase-1/IL-1β signaling pathway to decrease pyroptosis offering a protective effect during sepsis." (PMID 30779706, 2019). "In this study, we hypothesized that NLRP3 is activated in platelets in response to cecal ligation‐puncture (CLP) and is associated with multiorgan injury in response to polymicrobial sepsis." (PMID 31054188, 2019). "Elucidation of mechanisms downstream of platelet NLRP3 activation may increase our understanding of sepsis pathophysiology and lead to the development of novel therapeutic strategies to improve sepsis outcomes." (PMID 31054188, 2019). "To explore whether MRS could affect the NLRP3 inflammasome signaling pathway to improve sepsis injury, we measured the expression levels of p-P65, P65, pro-caspase-1, pro-IL-1β and NLRP3/caspase-1/IL-1β by Western blotting 12 and 24 h after CLP." (PMID 30779706, 2019). "Furthermore, most sepsis-related deaths are among patients whose NLRP3 activation is profoundly altered." (PMID 31221993, 2019). "Therefore, by monitoring the changes in NLRP3 and caspase-1, we observed pyroptosis of cortical neurons in rats with sepsis-induced brain injury after different treatments." (PMID 31775794, 2019). "This study is the first to examine platelet NLRP3 activation in sepsis." (PMID 31054188, 2019). "Finally, MRS suppressed the activation of the NLRP3/Caspase-1/IL-1β inflammasome signaling pathway to alleviate the tissue and cell damage induced by sepsis." (PMID 30779706, 2019). "Likewise, in a sepsis-induced ALI/ARDS murine model it has been shown that hemin inhibits NLRP3 inflammasome activation through the action of HO-1." (PMID 29868517, 2018). "While the NLRP3 inflammasome is crucial for host immunity, it is unclear if excessive activation of the inflammasome in sepsis may have detrimental effects on organ function and survival." (PMID 29488356, 2018). "However, dysregulation of NLRP3 activity leads to chronic inflammation and the development of several pathologies, such as neurodegeneration, metabolic disorders, and sepsis." (PMID 29951054, 2018). "In addition, activation of the NLRP3 inflammasome and upregulation of IL-1 were observed both in cardiac fibroblasts pretreated with lipopolysaccharide (LPS) and in a sepsis mouse model." (PMID 29850631, 2018). "Deregulated activation of NLRP3 is present in sepsis-associated ALI/ARDS in mice, and in the absence of NLRP3 activation there is a reduction in pro-inflammatory cytokine and neutrophil levels in bronchoalveolar lavage fluid." (PMID 29868517, 2018).
Sepsis (continued). "Inhibition of the NLRP3 inflammasome by using glyburide could ameliorate myocardiac dysfunction induced by sepsis." (PMID 29850631, 2018). "As ATP-induced NLRP3 inflammasome activation has critical roles in bacterial sepsis, we explored whether baicalin could ameliorate sepsis in a mouse model of bacterial infection in the peritoneal cavity." (PMID 29163487, 2017). "Likewise, decreased activation of IL-1β in Nlrp3 KO mice during sepsis resulted in decreased Il6 expression, which is a target of IL-1β and mediates atrophy." (PMID 28097512, 2017). "However, the specific interaction of melatonin with the NLRP3 inflammasome during sepsis in cardiac tissue remains to be clearly identified." (PMID 29104591, 2017). "Nlrp3 knockout mice showed reduced IL-1β serum levels in sepsis." (PMID 28097512, 2017). "Its effects on NLRP3-related inflammatory diseases including sepsis also await clarification." (PMID 29375379, 2017). "Based on these observations, it is possible that Nlrp3 KO mice have less overall inflammation during sepsis when compared to Nlrp3 WT animals and that not only decreased IL-1β levels but also reduced overall inflammation contributed to reduced muscle atrophy in septic Nlrp3 KO mice." (PMID 28097512, 2017). "As ATP-induced NLRP3 activation and pyroptosis plays a critical role in sepsis of bacterial infection, we finally explored whether scutellarin could attenuate bacterial sepsis in a mouse model of intraperitoneal infection." (PMID 29375379, 2017). "Furthermore, other recent publications report on the effect of melatonin treatment against NLRP3 complex assembly in radiation-induced mucositis, sepsis, and aging." (PMID 29104591, 2017). "As the pro-inflammatory effect of the NLRP3 inflammasome is deleterious, the discovery of effective and specific drugs that alter NLRP3 inflammasome function has the potential to improve the symptoms of sepsis and AKI." (PMID 26334271, 2015). "Therefore, the inflammation and expression of NLRP3 inflammasome was detected in sepsis-induced AKI." (PMID 26334271, 2015). "Previous studies suggested that NLRP3 inflammasome activity is positively regulated by ROS, so CO may inhibit NLRP3 inflammasome activation by decreasing ROS levels in kidney of sepsis-induced AKI." (PMID 26334271, 2015). "To assess whether the NLRP3 inflammasome/caspase-1 pathway would be activated in a polymicrobial model of sepsis we used the FIP model." (PMID 25216263, 2014). "The NLRP3 inflammasome is an intracellular multi-protein complex that triggers caspase-1 mediated maturation of interleukin-1β (IL-1β); one of the most potent mediators of inflammation and a major cytokine produced during severe infections, like sepsis." (PMID 25400921, 2014). "In order to determine whether the inhibition of the NLRP3 inflammasome has beneficial effects on a multimicrobial (peritonitis) mouse model of sepsis, we used the FIP model." (PMID 25216263, 2014). "It has been identified that estrogen can ameliorate some diseases such as sepsis, Parkinson’s disease, inflammatory bowel disease, spinal cord injury, multiple sclerosis, myocardial ischemia/reperfusion injury, and renal fibrosis, by inhibiting the NLRP3 inflammasome." (PMID 40458798, 2025). "Research indicates that tangeretin suppress the activation of the NLRP3 inflammasome mediated by ROS, indicating the possibility that tangeretin may offer protection against lung injury from sepsis through pyroptosis inhibition and this warrants further exploration." (PMID 39815349, 2025). "However, the effects of palmitoylation-assisted NLRP3 on sepsis-mediated immunity and inflammation across organs at stages remain unclear." (PMID 40461967, 2025). "Additionally, LL-37 has been shown to alleviate sepsis-induced acute lung injury by downregulating the expression of key components of the pyroptotic pathway, including NLRP3, caspase-1, and GSDMD, as well as downstream inflammatory factors in alveolar epithelial cells." (PMID 40072070, 2025).
Sepsis (continued). "Likewise, inhibition of NLRP3 inflammasome activation suggests Fas may reduce pyroptosis—an inflammatory form of cell death that worsens organ dysfunction in sepsis." (PMID 40699739, 2025). "Here, this study aims to investigate the potential mechanism of ET in reducing inflammation in sepsis based on macrophage autophagy and reveal whether ET restores the autophagic flux in macrophages, inhibit NLRP3 inflammasome activation in septic mice through the regulation of TRIM26." (PMID 40918153, 2025). "Consequently, targeting the NLRP3 inflammasome could be a novel and noteworthy area for therapeutic advances in neonatal infection/sepsis and preterm birth." (PMID 41149694, 2025). "Collectively, these studies underscore the diverse approaches and potential of nanocarriers in targeting NLRP3 inflammasome‐driven inflammation, particularly in conditions such as sepsis, and highlight promising therapeutic avenues for managing a variety of inflammatory disorders, like sepsis." (PMID 40599085, 2025). "Thus, NLRP3 inflammasome activation is crucial to the pathogenesis of sepsis." (PMID 40918153, 2025). "Additionally, in a mouse model for lung injury caused by sepsis, the application of MCC950 (an NLRP3 inhibitor) inhibited ferroptosis-associated biomarkers, whereas ferrostatin-1 (a ferroptosis inhibitor) led to a decrease in NLRP3 and proteins involved in pyroptosis." (PMID 39815349, 2025). "We wondered whether NLRP3 inflammasome was involved in inducing coagulation in MRSA sepsis." (PMID 38789414, 2024). "However, the mechanism of NLRP3 inflammasome activation in sepsis-induced lung injury remains unclear." (PMID 38698431, 2024). "The NLRP3 concentration in serum may be used as an additional biomarker of inflammation, which has already been applied to some inflammatory conditions, including periodontitis, sepsis, and peripheral arterial disease." (PMID 39100660, 2024). "Additionally, ethyl pyruvate may inhibit the release of HMGB1 and preserve mitochondrial integrity, playing a protective role against lethality induced by sepsis and endotoxemia by inhibiting NLRP3 inflammasome activation." (PMID 39623879, 2024). "However, high levels of NLRP3 can also result in poor predictive outcomes for sepsis." (PMID 38716051, 2024). "Our results show that CLP-sepsis resulted in a rise in the cardiac phosphorylation of IKK and, hence, activation of NF-κB pathway, which was associated with an increased expression of NLRP3 in the heart and augmented systemic release of the cardio-suppressive IL-1β." (PMID 39559354, 2024). "Furthermore, immunofluorescence staining demonstrated co-localization of the pyroptosis markers Caspase-1 and NLRP3 with the macrophage-specific antibody F4/80, providing further evidence that sepsis-induced lung injury can be prevented by inhibiting macrophage pyrolysis by GDF3." (PMID 38543054, 2024). "Therefore, we wondered whether HSPA8, as a major molecule in ubiquitin-protein degradation, has a regulatory role in NLRP3 ubiquitination modification during sepsis." (PMID 38698431, 2024). "Consequently, suppressing the activation of the NLRP3 inflammasome may be good for patients with sepsis." (PMID 37650025, 2023). "Therefore, targeting the NLRP3 inflammasome pathway might be a potential therapeutic strategy for sepsis patients with ARDS." (PMID 37649483, 2023). "On the other hand, systemic inflammatory states, such as sepsis, are accompanied by platelet activation, which may simultaneously activate mRNA maturation and NLRP3 inflammasome assembly, thereby forming a full process of production and release of the active cytokines." (PMID 37622117, 2023). "Reduced NLRP3 inflammasome-mediated IL-1β release and decreased caspase-3 concentrations, thus lead to inhibited apoptosis and pyroptosis alleviated pulmonary pathological damage and improved the survival rate of the sepsis mice via the MAPK/NF-κB/NLRP3 pathway." (PMID 38274788, 2023).